LOXL2 (lysyl oxidase like 2)
Diseases named in the same sentence as LOXL2 in open-access papers (continued):
Sharing a sentence is not in itself a finding about the gene and the disease.
tumor (continued). "However, there is more and more evidence indicating that lysyl oxidases also promote tumor cells metastasis by targeting intracellular proteins, such as histones or transcription factors, such as snail, in the cases of LOXL2 and LOXL3." (PMID 35682926, 2022). "Based on TCGA-LUAD transcriptome data, differential expression analysis showed that with the comparison of normal samples, DKK1 and LOXL2 expression were significantly increased in tumor tissues, whereas MGP and SLIT3 were markedly overexpressed in non-tumoral tissues." (PMID 36185284, 2022). "Both LOXL2 and L2Δ13 directly catalyzed the deacetylation of aldolase A at K13, resulting in enhanced glycolysis which subsequently reprogramed tumor metabolism and promoted tumor progression." (PMID 36209516, 2022). "Therefore, LOXL2/L2Δ13 stimulates aldolase mobilization to enhance its enzymatic activity, which in turn promotes glycolysis and tumor cell proliferation." (PMID 36209516, 2022). "Our findings highlight a hitherto-unknown mechanism by which LOXL2 and L2Δ13 catalyze the deacetylation of aldolase to stimulate its mobilization and enzymatic activity in glycolysis that in turn promotes tumor progression." (PMID 36209516, 2022). "Lung, liver and axillary metastases showed higher expression of Loxl2 in the tumor cells." (PMID 36002889, 2022). "Our study suggests that LOXL2 may exert its tumorigenic effects by potentiating tumor immune cell infiltration and immune checkpoint expression." (PMID 36254230, 2022). "LOXL2 regulates collagen cross-linking and deposition in primary tumor tissue." (PMID 36186418, 2022). "In addition, the correlation between LOXL2 expression and immune checkpoint markers (CD274, PDCD1, and CTLA-4) suggested a role for LOXL2 in immune regulation of tumor immunity." (PMID 36254230, 2022). "Moreover, LOXL2 expression was positively related to tumor grading, metastasis, and vasculogenic mimicry (VM)." (PMID 36293126, 2022). "LOXL2 is essential for the EMT process in various tumor cells." (PMID 36159334, 2022). "Diagnostic value was also found in another secretory enzyme lysyl oxidase like 2 (LOXL2), which was speculated to be involved in ECM remodeling and epithelial-mesenchymal transition, thus contributing towards tumor progression." (PMID 36430813, 2022). "Altered metabolism is a core hallmark of cancer, however, it remains unclear whether and how LOXL2 contributes to tumor metabolism." (PMID 36209516, 2022). "Overexpression of LOXL2 or LOXL3 in epithelial cells causes EMT, indicating that they may play a role in tumor growth." (PMID 36314741, 2022). "LOXL2 is a copper dependent amine oxidase involved in tumor invasion and metastasis." (PMID 36524120, 2022). "Interestingly, L2Δ13 in this assay also rescued tumor development more efficiently than full-length LOXL2." (PMID 36209516, 2022). "To investigate whether LOXL2-enriched sEV-treated fibroblasts affect tumor cell adhesion, we treated MRC5 cells with sEVs derived from normoxic Cal-27 cells, sEVs derived from hypoxic Cal-27 cells with or without LOXL2 KD." (PMID 34646366, 2021). "Overall, these studies suggest that LOX/LOXL2 may serve as a therapeutic target to prevent the emergence from tumor dormancy to overt metastases." (PMID 33987095, 2021). "Therefore, tumor-promoting LOXL2 can be delivered by sEVs that are derived from the tumor and stromal cells in hypoxic tumor microenvironment." (PMID 34646366, 2021). "Indeed, some LOX members (in particular LOXL2) promote tumour cell survival, regulate cell adhesion, motility and invasion, and remodel the TME." (PMID 33544155, 2021). "We then investigated whether LOXL2 mediates hypoxic sEV-induced tumor cell colonization in the lung." (PMID 34646366, 2021). "Recently identified another regulator of hypoxia-induced tumor growth is LOXL-2." (PMID 33639646, 2021). "This LOXL2 overexpression in tumor cells is induced by hypoxia, TGF-β and SMAD4 pathways." (PMID 34298680, 2021).
tumor (continued). "The LOXL2 concentration αρ is determined by the inherent traits of the primary tumor, and could be altered for example by LOXL2-suppressing drugs." (PMID 33807227, 2021). "Because collagen I fiber alignment is associated with increased tumor cell motility rate, and we observed an increase in 3D invasion within a collagen I matrix; OSM-induced LOXL2 may likely have an impact on metastasis." (PMID 34011405, 2021). "To get some idea of what might happen in practice for a localized tumor, we imagine that cells in some spherical region of radius R form a tumor of a constant cell density ρ and are emitting LOXL2 at a constant rate α." (PMID 33807227, 2021). "Thus, there is a need for better understanding the exact pathways by which areca nut extracts upregulate LOXL-2 in hypoxic tumor microenvironment." (PMID 33639646, 2021). "LOXL-2 has an important role in activation of fibroblasts in the tumor microenvironment." (PMID 33639646, 2021). "To further confirm that CD8+ T cells infiltrate into tumor tissues after combination therapy with anti-PD-L1 and LOXL2 inhibition or knockdown, we performed immunohistochemistry (IHC) stains for CD8 in primary and lung metastatic tumor tissues from the combinatorial treatment studies." (PMID 32908154, 2020). "Based on these findings, we hypothesized that remolding the tumor microenvironment via blocking LOXL2 may be an effective treatment for KIRC." (PMID 32970930, 2020). "Furthermore, while LOXL2 expression in the tumors was unchanged, tumor collagen packing density and lung colonization were decreased in BAPN-treated LM7-derived OS-bearing mice." (PMID 32686768, 2020). "The role of LOXL2 in CCA tumor promotion has been highlighted in recent years." (PMID 33371259, 2020). "Our study indicated that LOXL2 may promote VM formation and tumour metastasis by collaborating with SNAIL in HCC." (PMID 30506621, 2019). "In this study, we attempted to identify the effects of LOXL2 on tumour VM." (PMID 30506621, 2019). "Thus, tumor cell-derived LOXL2 in the microenvironment directly targets neighboring resident cells to promote a permissive local niche, in addition to its known role in collagen maturation." (PMID 31086173, 2019). "Tumor-secreted LOXL2 activates CAF through FAK signaling, and this may occur via enhanced ECM stiffness." (PMID 31061140, 2019). "In addition, the increased tissue rigidity in LOXL2-high tumors facilitates endothelial invasion of the tumor tissue, a critical step in neo-vessel formation, presumably by increasing motility via FAK signaling." (PMID 32118030, 2019). "Due to high expression of LOXL2 in tumor cells observed above, and the fact that LOXL2 is principally a secreted enzyme, we next evaluated the hypothesis that LOXL2 secreted from tumor cells in some way directly targets surrounding fibroblasts." (PMID 31086173, 2019). "We considered the notion that secreted LOXL2 could stimulate the proliferation of tumor cells in addition to neighboring stromal cells." (PMID 31086173, 2019). "Here, we entertained the notion that tumor cell-secreted LOXL2 may target non-tumor mesenchymal cells to stimulate proliferation." (PMID 31086173, 2019). "Moreover, tumor-derived LOXL2 was shown to activate CAFs through FAK activation mediated by β3 integrin." (PMID 31130685, 2019). "An additional complexity is the apparent feed forward requirement of tumor cells for LOXL2 activity to maintain LOXL2 expression that may be independent of PDGF signaling." (PMID 31086173, 2019). "Several studies have shown that LOX and LOXL2 promote angiogenesis to drive tumor metastasis." (PMID 30704479, 2019). "Additionally, several reports have shown a role for LOXL2 in other processes, including regulation of gene expression, tumor metastasis, and epithelial‐to‐mesenchymal transition (EMT)." (PMID 30387148, 2019). "Knockdown of highly expressed LOXL2 in PCa can reduce tumor cell invasion and migration." (PMID 29732010, 2018).
tumor (continued). "Overexpression of LOX/LOXL2 increased tumor establishment and initial growth of the 4T1 tumors." (PMID 29780168, 2018). "However, the influence of Loxl2 on the dermis during development and tumour formation is unexplored." (PMID 29953488, 2018). "Based on these observations, we speculated that Loxl2 might have an influence on the dermal tumour microenvironment." (PMID 29953488, 2018). "Several studies have described LOXL2 induction of tumor progression and fibrosis." (PMID 29089463, 2017). "This further confirms our hypothesis that tumor-derived LOXL2 upregulates αSMA positivity within the tumors." (PMID 28199967, 2017). "In human tumours with overexpression of LOXL2, the observed regions with intracellular accumulation of LOXL2 could reflect this situation." (PMID 28332555, 2017). "However, the role of LOXL2 expression in cancer cells (referred as ‘cancer cell-derived LOLX2’ in this report) in hypoxic tumor microenvironment remains incompletely understood, especially regarding molecular mechanisms." (PMID 28449718, 2017). "Furthermore, to understand the mechanism how cancer cell-derived LOXL2 can regulate HCC progression in hypoxic tumor microenvironment, we performed microarray analysis." (PMID 28449718, 2017). "The pro-angiogenic effects of LOXL2 observed in our in vivo tumor studies have been further supported by previous research where LOXL2 has been demonstrated to be necessary for collagen IV assembly and organization in the endothelial basal lamina, a process critical to angiogenesis." (PMID 28199967, 2017). "Tumour-secreted LOXL2 activates fibroblasts and induces collagen remodelling in the ECM11." (PMID 26804196, 2016). "Importantly, increasing evidence indicates that high LOXL2 expression correlates with tumor grade and poor survival." (PMID 27008697, 2016). "Notably, our findings demonstrate that the tumor microenvironment can promote DTC to acquire CSC-like phenotype by inducing LOXL2 expression, thus mediating their transition to metastatic outgrowth." (PMID 27655685, 2016). "However, many reports have suggested different intracellular roles for LOXL2, including the ability to regulate gene transcription and tumor progression." (PMID 24414204, 2014). "Our findings indicate that high expression of LOXL2 promotes tumor-like phenotype in normal mammary cells and suggest that LOXL2 may be used as a marker to identify patients most likely to respond to anti-ErbB2 therapy." (PMID 23971878, 2013). "Another member of the lysyl oxidase family, LOXL2, also shows tumor-promoting effects." (PMID 22509805, 2012). "However, this is probably not the only mechanism by which Loxl2 modulates tumor cell invasiveness and more studies are required in order to understand the mechanisms by which Loxl2 enhances tumor cells invasiveness." (PMID 19948022, 2009). "Loxl2 over-expression affects the degradation of the transcription factor snail resulting in the inhibition of the expression of E-cadherin, a known marker of epithelial to mesenchymal transition and a key regulator of tumor cells invasiveness." (PMID 19948022, 2009). "This cross-platform and repeatable expression pattern suggests that LOXL2 may affect the tumor microenvironment through dual mechanisms, participate in the regulation of tumor cell malignant phenotype and affect the function of immune cells through stromal cell remodeling." (PMID 40756111, 2025). "Additionally, our findings revealed that patients with triple‐negative breast cancer receiving neoadjuvant chemotherapy showed lower levels of LOX and LOXL2 expression in their tumour tissues than those who were sensitive to taxanes, anthracyclines and platinum agents." (PMID 40179101, 2025). "Our data suggest that inhibition of CTSD and LOXL2 would not only have an anti-proliferative effect but may also be an effective therapeutic approach for eradicating residual disseminated tumor cells or maintaining them in a dormant state to avert cancer recurrence." (PMID 41185039, 2025).
tumor (continued). "We have found that high expression of LOXL2 is associated with lymph node metastasis and a poor prognosis in ESCC and that LOXL2 induces cytoskeletal reorganization and ezrin phosphorylation, which subsequently promotes tumour cell invasion and metastasis in ESCC." (PMID 37753805, 2023). "In addition, LOXL2 may also promote the development of LUAD by influencing cell–cell interactions in the tumor microenvironment." (PMID 37886979, 2023). "Consequently, it is hypothesized that tumor immune infiltration exerts an influential role in LOXL2-mediated HCC development." (PMID 36254230, 2022). "Consequently, combining the expression of LOXL2 between tumor and normal tissues and its prognostic value, LOXL2 may be utilized as an unfavorable prognostic biomarker in patients with LIHC." (PMID 36254230, 2022). "Moreover, LOXL2 couples the Warburg effect to tumor growth and metastasis in PDAC." (PMID 34836938, 2021). "Besides, many studies have shown that the abnormal expression of LOXL2 in a variety of cancers is related to epithelial-mesenchymal transition, metastasis, poor prognosis, resistance to radiotherapy and chemotherapy, and tumor progression." (PMID 34040139, 2021). "Since LOXL2 affects the pathophysiological processes of cancer, such as cell adhesion and invasion and promotes endothelial tube formation by cross–linking collagen IV in the vascular system, its expression may be related to tumor angiogenesis and progression." (PMID 34393991, 2021). "Interestingly, we have shown that the propeptide of LOX, which has anti-angiogenic and anti-tumoral activity, bound to LOXL2, which promotes tumor invasion and metastasis, raising the question of the regulation of angiogenesis and tumorigenesis at the level of the LOX family interactome." (PMID 33383846, 2020). "Some effects of LOXL2 on tumor cells might thus be mediated by this integrin." (PMID 33383846, 2020). "The analysis of the relationship between LOXL2 and the clinicopathological characteristics showed that the cytoplasmic LOXL2 overexpression was not correlated with the patients’ age or tumour size but was correlated with clinical metastasis (P = 0.002; and tumour grade (P = 0.04)." (PMID 30506621, 2019). "Likewise, small LOXL2 inhibitors decrease tumor angiogenesis and restrict tumor growth." (PMID 31615160, 2019). "However, their amino-terminal regions are different, determine their different roles in protein-protein interaction To date, only few soluble factors such as tumor secreted LOXL2, exosomes exhibit important pathological roles in formation of pre-metastatic niche in HCC metastasis." (PMID 29728125, 2018). "Interestingly, high expression of 4 genes targeted by anti-tumor miRNAs was significantly associated with poor prognosis of patients with RCC according to TCGA database analyses (UHRF1: p = 4.87E-06, LOXL2: p = 0.0343, PLOD2: p = 0.000855 and SKA1: p = 1.44E-07)." (PMID 29928475, 2018). "Based on the posttranslational features of LOXL2 we hypothesized that the perinuclear localization of the protein in human tumours could reflect LOXL2 accumulation in the ER because under overexpression conditions the posttranslational processing turns out to be a limiting step." (PMID 28332555, 2017). "Further GO analysis of biological process about the upregulated DEGs between LOXL2 vs Control and CoCl2 vs Control indicated that hypoxia may affect biological process of tumor, such as mitotic cell cycle, developmental growth, which were also impacted by upregulating LOXL2 expression." (PMID 28449718, 2017). "Specifically hypoxia, which is part of the tumor microenvironment milieu, previously shown to play an important role in establishing pre-metastatic niche, can induce endogens expression of cytoplasmic and nuclear expression of LOXL2 resulting in EMT and a CSC-like phenotype of MCF-7 cells." (PMID 27655685, 2016).
tumor (continued). "Preliminary observations indicate a decrease in the tumor volume and weight of mice in the sh-LOX, sh-LOXL1, sh-LOXL2, sh-LOXL3, and sh-LOXL4 groups compared to the sh-NC group." (PMID 40270974, 2025). "CSR‐related genes (COL1A1, LOXL2, LUM, FN1, and TGFB1) reflect extracellular matrix deposition and stromal activation, hallmarks of invasive tumor behavior." (PMID 41407509, 2025). "Together, MMA induces LOXL2 expression in PSCs, increasing linear ECM alignment and accelerating tumor progression." (PMID 40425551, 2025). "CST significantly suppressed CCN2, LOXL2, DDIT4, and FN1, key drivers of ECM remodeling and angiogenesis, indicating that CST disrupts the structural and metabolic axes sustaining tumor progression." (PMID 41279995, 2025). "According to our research, regions of tumours with high LOX and LOXL2 levels also had higher expression of CD68 and CD206, which were known to be markers of macrophages and M2 macrophages, respectively." (PMID 40179101, 2025). "Our identification of PEAR1 as a protein which efficiently binds CTSD and LOXL2 and thereby inhibits their pro-proliferative activity in the context of tumor cell dormancy also suggests PEAR1 as a tool to lower levels of free CTSD and LOXL2." (PMID 41185039, 2025). "By integrating phenotypic assays with transcriptomic profiling, distinct downstream effectors were revealed—including TRAF2 and LOXL2—that connect TFAM dysregulation to cell cycle control, metabolic reprogramming, and tumor invasiveness." (PMID 41226485, 2025). "Functionally, MMA promotes LOXL2 expression in pancreatic stellate cells (PSCs), increases linear ECM alignment in normal pancreatic tissues, and facilitates tumor progression." (PMID 40425551, 2025). "The results indicated a significant increase in the expression of INF-γ and TNF-α in the tumor tissues of mice from the sh-LOX, sh-LOXL1, sh-LOXL2, sh-LOXL3, and sh-LOXL4 groups compared to the sh-NC group." (PMID 40270974, 2025). "This led us to propose a model in which PEAR1 promotes tumor cell dormancy by extracellular binding of CTSD and LOXL2, thereby preventing CTSD and LOXL2 to exert pro-proliferative activity." (PMID 41185039, 2025). "RT-qPCR and WB techniques were used to detect the expression of LOX, LOXL1, LOXL2, LOXL3, and LOXL4 in tumor tissues." (PMID 40270974, 2025). "In the hypoxic tumor microenvironment of HCC, HIF-1α is activated as a transcription factor and directly upregulates the expression of LOXL2." (PMID 41019994, 2025). "Across data set analysis shows that LOXL2 genes show significant cell type specific expression pattern: in the CCGA data mainly occurred in macrophages and tumor cells, while in validation specificity high expression in malignant cells and stromal cells." (PMID 40756111, 2025). "Immunofluorescent staining revealed increased infiltration and exhaustion of CD8+ T cells in the tumor tissues of mice in the sh-LOX, sh-LOXL1, sh-LOXL2, sh-LOXL3, and sh-LOXL4 groups, compared to the sh-NC group." (PMID 40270974, 2025). "Both tumor cells and CAFs secrete LH2, which increases tumor stiffness by upregulating LOXL2 in response to high matrix stiffness." (PMID 40211368, 2025). "LOXL2 regulates ECM remodeling and stiffness, a key factor in tumor invasion and metastasis, often via ZEB1-mediated upregulation." (PMID 41164190, 2025). "CAFs and TAMs were found to be enriched in tumour regions characterised by enhanced expression levels of LOX and LOXL2 compared to regions with lower expression levels of these proteins." (PMID 40179101, 2025). "The results demonstrated a significant decrease in the expression of Ki67 protein in tumor tissues from sh-LOX, sh-LOXL1, sh-LOXL2, sh-LOXL3, and sh-LOXL4 mice, compared to the sh-NC group." (PMID 40270974, 2025). "Flow cytometry analysis revealed a significant reduction in the proportion of M2 macrophages in the tumor tissues of sh-LOX, sh-LOXL1, sh-LOXL2, sh-LOXL3, and sh-LOXL4 groups of mice compared to the sh-NC group." (PMID 40270974, 2025).